JAK2 (Janus kinase 2)
Diseases named in the same sentence as JAK2 in open-access papers (continued):
Sharing a sentence is not in itself a finding about the gene and the disease.
Hypertension (continued). "Results from the PPI analysis identified IL-8, JAK2, AGTR1, and BCR to be the centers of genomic changes, in which AGTR1 was the target of hypertension, the common cause of cardiac remodeling triggered by mechanical stress." (PMID 31772688, 2019). "JAK2/STAT3 activation, however, is tightly associated with AngII hypertension, even when caused by physiologic levels of AngII." (PMID 26486161, 2015). "Moreover, therapeutic suppression of JAK2 has been shown to reduce the progression of hypertension in Ang II-infused rats." (PMID 36324691, 2022). "After narrowing down the possible candidates, telmisartan, a clinically used medicine against hypertension, could be selected as one of the strongest JAK2 inhibitors from 821 drugs." (PMID 33917914, 2021). "Furthermore, it was shown that pharmacological inhibition of JAK2 diminished the development of hypertension in Ang II-infused animals." (PMID 31703282, 2019). "Moreover, inhibition of JAK2 has been shown to reverse and prevent vasoconstriction in arteries, which suggests targeting JAK2 may be a therapeutic strategy for hypertension." (PMID 38474730, 2024). "Importantly, CC-509 was optimized away from and has modest activity against cellular KDR and Jak2, kinases that when inhibited in a preclinical and clinical setting may promote hypertension and neutropenia, respectively." (PMID 26756335, 2016). "There was an interaction between the SOCS3, JAK2 and STAT3 genes and hypertension/triglycerides." (PMID 34991691, 2022). "The stimulation of JAK2/STAT3 pathway via Ang II has been shown in experimental studies, both in vitro and in vivo, and therefore play a vital role in the development of Ang II-dependent hypertension." (PMID 36324691, 2022). "Since phosphorylation of JAK2 was regulated by IL13Rα2, we tried to screen a novel JAK2 inhibitor from the FDA-approved drug library and selected telmisartan, a clinically used medicine against hypertension, as one of the strongest candidates." (PMID 33917914, 2021). "JAK2/STAT3 signaling also is not required for blood pressure maintenance on LS diet, and appears uniquely linked to AngII hypertension, even at physiologic plasma AngII concentrations." (PMID 26486161, 2015).
liver fibrosis (30 papers, 2015 to 2025). "PZW mitigated hepatic fibrosis, with its effect associated with the inhibition of the IL-6/JAK2/STAT3 and TGF-β/Smad2/3 signaling pathways and through raising the MMP1/TIMP-1 ratio." (PMID 41293246, 2025). "PZW mitigated hepatic fibrosis in association with IL-6/JAK2/STAT3 and TGF-β/Smad2/3 signaling pathway inhibition favoring MMP1/TIMP-1 ratio that attenuated collagen deposition and promoted collagen degradation." (PMID 41293246, 2025). "In conclusion, the current study found that PGC-1α deficiency deteriorated the I/R-induced liver fibrosis by enhancing the IL-6/JAK2/STAT3 signaling and M2-type macrophage polarization." (PMID 37679346, 2023). "JQ-1 from the SEA relieves liver fibrosis caused by S. japonicum infections by inhibiting JAK2/STAT3 signaling." (PMID 36986363, 2023). "Angiotensin II is a potent inducer of liver fibrosis, as determined by experimental and clinical observations, and AGTR1 was recently implicated in the development of liver fibrosis via activation of JAK2." (PMID 29029395, 2017). "Moreover, Jak2 overexpression reversed the inhibition of liver fibrosis caused by CXCL14 knockdown in vivo." (PMID 39358917, 2024). "Similarly, Jak2 overexpression mitigated the effects of CXCL14 deficiency in a BDL‐induced liver fibrosis model." (PMID 39358917, 2024). "The chemokine CXCL14 is also involved in the ATF3/Cxcl14/Jak2 signaling axis in hepatic stellate cells responsible for liver fibrosis." (PMID 40893164, 2025). "The roles of JAK2/STAT3 and TGF-β/Smad2/3 regulatory pathways are examined specifically as it is found to be a crucial pathogenic mediator of liver fibrosis." (PMID 41293246, 2025). "A recent study demonstrated that JAK2/STAT3 functions downstream of the HSP27 pathway in liver fibrosis." (PMID 40230054, 2025). "PZW alleviated hepatic fibrosis in vivo, primarily by inhibiting collagen accumulation through navigating IL-6/JAK2/STAT3 and TGF-β/Smad2/3 signaling pathways." (PMID 41293246, 2025). "Liver fibrosis was characterized by collagen deposition and activation of Jak2-Stat3 signaling, resulting in hepatocyte apoptosis." (PMID 41091718, 2025). "The development of specific Jak2‐targeting antibodies as a therapeutic approach for liver fibrosis warrants further investigation, potentially enhancing the translational relevance of these findings." (PMID 39358917, 2024). "Findings revealed that the specific deletion of CXCL14 in HSCs suppressed liver fibrosis in mice via the activating transcription factor 3 (ATF3)/CXCL14/RUNX1/JAK2 signalling pathway." (PMID 39358917, 2024). "In summary, these results indicate that CXCL14 facilitates HSC activation and liver fibrosis through the Jak2 pathway." (PMID 39358917, 2024). "This discovery aligns with previous studies that highlight Jak2's significant role in liver fibrosis, where both animal models and human tissue analyses have demonstrated Jak2 upregulation." (PMID 39358917, 2024). "JAK2/STAT3 signaling is a research hotspot in fibrotic disease, but the role of JAK2/STAT3 in the progression of hepatic fibrosis remains controversial." (PMID 38074679, 2023). "Most literature studies have reported that inhibiting JAK2/STAT3 signaling of HSC alleviates hepatic fibrosis both in vivo and in vitro." (PMID 38074679, 2023). "More importantly, administration with AAV8-PGC-1α rescued the I/R-induced liver fibrosis by inhibiting the IL-6/JAK2/STAT3 signaling and M2-type macrophage polarization in the liver." (PMID 37679346, 2023). "We further analyzed the relationship between the expression of JAK1 and JAK2 and the degree of liver fibrosis in mice." (PMID 35382859, 2022). "JAK2/STAT3 activation has been previously associated with the ability of TGF-β to induce pulmonary and liver fibrosis, epithelial-mesenchymal transition, and cancer cell migration/invasion." (PMID 34383713, 2021).
liver fibrosis (continued). "In view of the finding that autophagic death plays a significant role in progression of hepatic fibrosis, we examined the potential impact of the JAK2/STAT3 pathway on regulation of cellular autophagy." (PMID 32233073, 2020). "Suppression of JAK2/STAT3 pathway has been showed to ameliorate liver fibrosis in rat in a recent study." (PMID 32233073, 2020). "TGF‐β1/Smad2/3 and JAK2/STAT3 pathways are closely associated with the therapeutic effects of PSS, supporting its potential as an effective treatment agent for hepatic fibrosis." (PMID 32233073, 2020). "Our group has demonstrated several times that the signaling cascade via JAK2, RhoA, and Rho-kinase signaling is upregulated in liver fibrosis and located mainly in myofibroblast-like activated HSC." (PMID 26696895, 2015). "However, Jak2 overexpression reversed the suppression of liver fibrosis due to CXCL14 knockdown, as evidenced by hyp quantification, Masson, and Sirius red staining." (PMID 39358917, 2024). "To further elucidate the functional relationship between CXCL14 and Jak2, we investigated whether CXCL14 promotes HSC activation and liver fibrosis through Jak2." (PMID 39358917, 2024). "JAK1 and JAK2 have been implicated in fibrosis and cancer as a fibroblast-related marker; however, their role in liver fibrosis has not been elucidated." (PMID 35382859, 2022). "Furthermore, angiotensin II was reported to induce hepatic fibrosis through the Janus kinase 2 (JAK2)-mediated intracellular action in HSCs." (PMID 34938271, 2021). "In the fibrotic liver, JAK2/STAT3 pathway is also able to influence liver fibrosis." (PMID 35432812, 2021). "Furthermore, JAK2/STAT3 pathway–related autophagy was also identified as a potential therapeutic target for hepatic fibrosis in our study." (PMID 32233073, 2020). "Our study confirms the critical role of THBS1 in RILI and identifies it as a mediator of hepatic fibrosis in RILI through PDGF/PDGFR and JAK2/STAT3 signaling pathways." (PMID 41394148, 2025). "Meanwhile, calycosin can increase estrogen receptor β (ERβ) expression, and then activate the subsequent Janus kinase 2 (JAK2)-STAT3 to inhibit hepatic stellate cells’ activation and collagen deposition against carbon tetrachloride-induced liver fibrosis." (PMID 41463300, 2025). "In both in vitro and in vivo liver fibrosis model, it suppresses HSC activation by inhibiting TGF-β1/Smad3 pathway thus reduces α-SMA and collagen I expression as well as targets JAK2/STAT3 pathway to regulate cell proliferation and apoptosis." (PMID 41293246, 2025). "In fibroblasts and fibrotic diseases, such as systemic sclerosis and CCl4-induced liver fibrosis, another SMAD-independent TGF-β1 activation pathway has been described that activates JAK2 and STAT3." (PMID 39060930, 2024). "In another study, it was demonstrated that activation of Janus kinase-2 (JAK-2) induced hepatic fibrosis is mediated through stimulation of ATR1 and prevented by pharmacologic inhibition of JAK-2." (PMID 37189076, 2023). "Since the activation and proliferation of HSCs in the main trigger for liver fibrosis and subsequent liver disease, to investigate the role of JAK1 and JAK2 on HSCs, LX-2 cells were transfected with siJAK1, siJAK2, or both of them." (PMID 35382859, 2022). "However, the role of JAK1 and JAK2 in liver fibrosis remains unclear." (PMID 35382859, 2022). "Therefore, JAK1 and JAK2 might play a key role in the process of liver fibrogenesis, and its potential inhibitor, Ruxolitinib, may be clinically useful in preventing or treating liver fibrosis." (PMID 35382859, 2022). "Our results collectively suggest that PSS prevents hepatic fibrosis by suppressing inflammation, promoting ECM decomposition and inactivating HSCs through the TGF‐β1/Smad2/3 and JAK2/STAT3 pathways." (PMID 32233073, 2020).
liver fibrosis (continued). "Several important signaling pathways, such as mTOR/HIF-1α, TGF-β1/Smads, and JAK2/STAT6, are involved in the effect of paeoniflorin on activated HSC and ECM inhibition during liver fibrosis." (PMID 32410996, 2020). "Molecular biology verified that THBS1 could mediate hepatic fibrosis by participating in the activation of the PDGF/PDGFR signaling pathway, followed by the activation of the JAK2/STAT3 signaling pathway, ultimately mediating liver fibrogenesis." (PMID 41394148, 2025). "In the presence of inflammation, interleukin-6 (IL-6) could activate janus kinase 2 (JAK2)-signal transducer and activator of transcription 3 (STAT3) signaling pathway of which has been reported to lead to liver fibrosis." (PMID 41293246, 2025). "IPA of MYOC/CCL19 fibroblast gene expression correlating with the mRSS revealed several prominent pathways: senescence, hepatic fibrosis signaling, IL-6 signaling, STAT3 signaling, TGF-β signaling, protein ubiquitination, JAK/Stat signaling, and role of JAK1, JAK2 and TYK2 in interferon signaling." (PMID 35943798, 2022). "In conclusion, PSS prevents hepatic fibrosis by suppressing inflammation, promoting extracellular matrix (ECM) decomposition and inactivating hepatic stellate cells through mechanisms involving the TGF‐β1/Smad2/3 and JAK2/STAT3 pathways in vivo and in vitro." (PMID 32233073, 2020).
ulcerative colitis (30 papers, 2011 to 2026). An inflammatory bowel disease involving the mucosal surface of the large intestine and rectum. "SNPs (rs10758669 and 10975003) in JAK2 are considered susceptibility factors for Crohn's disease (CD) in the German population and ulcerative colitis (UC) in the Korean population." (PMID 27965977, 2016). "In contrast, ruxolitinib, a selective JAK1/JAK2 inhibitor, has demonstrated efficacy in controlling both PV and inflammatory disorders such as ulcerative colitis." (PMID 41487987, 2026). "In short, Rauwolfia polysaccharide can inhibit the progress of ulcerative colitis through NOS2-mediated JAK2/STAT3 pathway." (PMID 38626146, 2024). "GGQLD has been shown to alleviate ulcerative colitis by inhibiting the IL-6/JAK2/STAT3 signal transduction pathway and restoring the homeostasis of Th17 and Treg cells within colon tissues." (PMID 37370132, 2023). "CA has been reported to be able to reduce the inflammatory response in ulcerative colitis by modulating the JAK2/STAT3 pathway." (PMID 35645793, 2022). "JAK2, a member of the intracellular tyrosine kinase family, is a potential target in the treatment of ulcerative colitis, as it regulates pathophysiological processes, such as inflammatory response, apoptosis, and cell cycle, primarily through its involvement in the JAK-STAT signaling pathway." (PMID 37200837, 2023). "The data demonstrated that LREE could significantly inhibit the production of IL-6 and phosphorylation of STAT3, JAK1, JAK2 in ulcerative colitis model mice." (PMID 34093175, 2021). "Western blot analysis and qPCR analysis in IEC6 cells stimulated by IL-6 in vitro revealed that EHLJ7 could cooperate with butyrate to exert its anti-ulcerative colitis effect by inhibiting the activation of JAK2/STAT3/SOCS1 pathway." (PMID 32038241, 2019). "Therefore, we speculate that Rau can inhibit the progress of ulcerative colitis through NOS2-mediated JAK2/STAT3 pathway." (PMID 38626146, 2024). "Further study indicated that EHLJ7 could cooperate with butyrate to exert its anti-ulcerative colitis effect by inhibiting the activation of janus kinase 2 (JAK2)/signal transducer and activator of transcription 3 (STAT3)/suppressor of cytokine signaling 1 (SOCS1) pathway." (PMID 32038241, 2019). "Our result seems also in parallel with an in vitro study, which was conducted on an acetic acid-induced ulcerative colitis model in rats and proved the inhibitory effect of nifuroxazide on STAT3/JAK2 signaling." (PMID 40925930, 2025). "To further explore the relationship among SCFAs, JAK2, STAT3, and SOCS1 and the development of ulcerative colitis, we initially observed changes in inflammation-related indicators in vivo." (PMID 32038241, 2019).
autoimmune disease (28 papers, 2011 to 2025). A disorder resulting from loss of function or tissue destruction of an organ or multiple organs, arising from humoral or cellular immune responses of the individual to their own tissue constituents. "Noteworthily, the coexistence of DM and ET with JAK2 V617F mutation indicated the possible complex interaction between hematologic and autoimmune diseases." (PMID 40574830, 2025). "Furthermore, some of these genes have been associated with susceptibility to the development of autoimmune diseases—JAK2, BACH2, and NCF1." (PMID 39598118, 2024). "Notably, suppressor of cytokine signaling 1 (SOCS1), which naturally limits the activation of Jak2 through binding interactions, is often deficient in autoimmune disease patients." (PMID 35505065, 2022). "JAK2 and TYK2 are members of the JAK family that are linked to multiple cytokine receptor signaling pathways in the pathogenesis of autoimmune disorders." (PMID 38674328, 2024). "The dysregulation of the JAK2/STAT3 pathway is associated with various cancers and autoimmune diseases." (PMID 38794198, 2024). "Baricitinib, a JAK1 and JAK2 inhibitor, was approved for the treatment of RA and widely used in many other autoimmune diseases." (PMID 36793118, 2023). "AC430 is an oral, potent Jak2-selective inhibitor intended for autoimmune diseases and cancer with an IC50 value of 28 nM." (PMID 34680353, 2021). "Variations within three of these genes (JAK2, BACH2, and NCF1) previously have been associated with autoimmune diseases." (PMID 33903979, 2021). "Activated Jak2-Stat5 signaling can be readily targeted by the second-generation Jak2-inhibitors that have been developed for myeloproliferative and autoimmune disorders and hematological malignancies." (PMID 34680353, 2021). "We identified genetic variations in JAK2, BACH2, and NCF1 that have been associated with autoimmune diseases such as inflammatory bowel disease and chronic granulomatous disease." (PMID 33903979, 2021). "Further, in patients with MPN, a correlation between JAK2 V617F positivity and prior autoimmune disease has been observed." (PMID 32967227, 2020). "Further work focusing on the ability of each JAKi to modulate key aspects of innate immune activation and JAK2 signaling may explain the anti-inflammatory activities of JAKi for treatment of autoimmune diseases." (PMID 32539713, 2020). "While pan-JAK inhibitors such as tofacitinib and ruxolitinib have demonstrated clinical success in autoimmune diseases, selective inhibition of JAK3 remains limited because of the high sequence similarity within ATP-binding pockets of JAK1, JAK2, and JAK3." (PMID 41385500, 2025). "These first-generation inhibitors simultaneously bind to JAK1, JAK2, JAK3, TYK2, and other homologous targets, thereby blocking multiple downstream signaling pathways, thereby treating a variety of autoimmune diseases." (PMID 40746612, 2025). "JAK1 is closely related to inflammation, cancer, immunity, and other diseases, JAK2 is primarily related to diseases of the blood system, and JAK3 is related to a variety of autoimmune diseases." (PMID 40746612, 2025). "Using a selective inhibitor of JAK2 rather than pan-JAK inhibitors avoids the potential complication of immunosuppression while targeting critical signaling pathways involved in autoimmune disease progression." (PMID 21510883, 2011).